HGF (hepatocyte growth factor)
Diseases named in the same sentence as HGF in open-access papers (continued):
Sharing a sentence is not in itself a finding about the gene and the disease.
tumor (continued). "HGF promotes tumor BAC cell spreading and worsens its prognosis." (PMID 31799175, 2019). "However, incubation of tumour cells with either M2-CM or exogenous HGF significantly increased the expression and phosphorylation of c-Met." (PMID 31130723, 2019). "Finally, the inhibition of the tumor–stroma interaction by MET/HGF interception induces stroma remodeling, which results in increased drug delivery and restoration of the response to gemcitabine." (PMID 30544501, 2018). "This directional streaming is possible by HGF/c-Met signaling pathway between endothelial cells and tumor cells; and c-Met inhibitors could be a potential target to block tumor cell streaming and metastasis." (PMID 29983921, 2018). "Therefore, tumor and stromal cells communicate with each other through HGF, creating a microenvironment that contributes to cancer progression." (PMID 30352967, 2018). "Given that HGF is a well-known prognostic factor for MM progression and acts as pro-survival cytokine for MM tumor cells, it is likely that in human clinical trials HGF neutralization will add further anti-proliferative potential to MP0250 antiangiogenic effect." (PMID 29568363, 2018). "Consequently, the aberrant activation of this HGF/c-MET signaling pathway promotes tumor cell proliferation and angiogenesis, inhibition of apoptosis, and EMT programming and is linked to an overall poor patient prognosis and survival rate." (PMID 29725606, 2018). "However, in tumor cells, aberrant activation of the HGF/c-Met pathway and stimulation of Wnt pathway block phosphorylation and acetylation of β-catenin through different signals." (PMID 29455668, 2018). "In turn, the tumor cells themselves produce cytokines, such as fibroblast growth factor 2 (FGF-2) and platelet derived growth factor (PDGF), to continuously recruit more fibroblasts, and then these fibroblasts generate even greater amounts of HGF, thus contributing to the growth of the tumor mass." (PMID 29342862, 2018). "Finally, PC‐9/NC tumours disappeared after 12 days of gefitinib treatment, whereas PC‐9/HGF tumours were slightly suppressed following gefitinib treatment." (PMID 29664235, 2018). "In addition, inhibition of HGF and c-Met signaling pathway has resulted in tumor reduction and progression in pancreatic cancer which paves the way for effective therapeutic approach." (PMID 30344239, 2018). "Gene set enrichment analyses of GC samples from TCGA and GSE62254 showed that high HGF expression was positively correlated with tumor growth and metastasis, which were confirmed by both functional experiments of cell proliferation, migration, and invasion in vitro and in animal models." (PMID 30158543, 2018). "However, many NSCLC patients eventually became resistant to alectinib and one common mechanism of acquired resistance to ALK TKIs is the secretion of HGF into the tumor microenvironment, leading to HGF-dependent c-Met signaling." (PMID 30134579, 2018). "Since JJN3 cells secrete high levels of the osteoblast inhibitory factor HGF, a reduction in tumour volume may prevent the development of bone disease." (PMID 29924867, 2018). "The origin of HGF present in the tumor microenvironment is unknown and HGF could be synthesized by a variety of tissues throughout the body, such as the liver itself or by the adipose tissue." (PMID 30214428, 2018). "Conversely, approaches to promote immune tolerance via HGF/Met in immune cells could concurrently stimulate potential tumor cells toward invasive growth." (PMID 29616031, 2018). "Previous studies have proven that HGF induced c-Met activation plays a fundamental role in angiogenesis and tumour progression in colorectal cancer by avoiding anti-angiogenic therapy and maintaining the glucose uptake and utilization by inducing GLUT1 expression." (PMID 30344239, 2018).
tumor (continued). "Because HGF is a pleiotropic cytokine that also promotes endothelial cell proliferation, migration, and capillary formation, tumor cell-derived HGF in autocrine tumors may stimulate vascular formation via paracrine activation." (PMID 30208970, 2018). "Connective tissue-derived stromal cells in the body secrete growth factors, like hepatocyte growth factor (HGF), that support regular cell division, but their interaction with cancer cells can be deleterious as they provide an extracellular matrix for tumor progression." (PMID 29342862, 2018). "In this sense, miR-26a may well alleviate tumor angiogenesis of HCC via blocking HGF/c-MET pathway and it might be a novel therapeutic strategy for HCC patients with aberrant HGF and c-MET." (PMID 30360560, 2018). "•Baseline Ang-1 and HGF significantly correlated with the gross tumor volume." (PMID 29398577, 2018). "It has been observed that cytokines hepatocyte growth factor (HGF), osteopontin (OPN), and stromal-derived factor 1α (SDF-1), secreted from tumor associated cells, increase CD44v6 expression by activating the Wnt/β-catenin pathway, which promotes migration and metastasis." (PMID 30383826, 2018). "Disrupting the HGF/c-Met signaling may interfere with tumor cell scattering thus affecting the metastasis dissemination." (PMID 29455657, 2018). "In HGF-autocrine tumors, tumor-derived HGF may promote angiogenesis via promoting vasculature formation by endothelial cells." (PMID 30208970, 2018). "Finally, in vivo experiments confirmed that restoration of miR-16 expression in fibroblasts reduced their ability to promote tumor growth and that HGF plays a central role in the pro-tumorigenic activity of fibroblasts." (PMID 29558956, 2018). "Thus, the mutual interaction between tumor and stromal cells mediated by tumor-derived HGF-inducers and stroma-derived HGF, stimulates tumor cell invasion and metastasis." (PMID 30352967, 2018). "Clinical impact may be observed in advanced cancers where the tumor cells encounter distant microenvironments that manifest high levels of HGF or NRG1β." (PMID 29550255, 2018). "Hepatocyte growth factor (HGF) is another molecule inducing tumor angiogenesis." (PMID 30186533, 2018). "Importantly, HGF-induced tumor cell motility and invasion are accompanied by an increase in cell dissociation and protease production [e.g., MMP-2 and urokinase-type plasminogen activator (uPA)]." (PMID 30352967, 2018). "Importantly, the combination of miR‐1‐3p (or miR‐206) and gefitinib reduced the size of PC‐9/HGF tumours." (PMID 29664235, 2018). "In contrast, HGF treatment induced single cell dissemination similar to the untreated control and did not cause an increase in tumour volume." (PMID 28706234, 2017). "However, the greatest reduction in tumor volume (to 17.9 ± 2.2 % of control mice receiving IgG treatment) was seen in the group of mice that received triple therapy (HGF inhibition + c-MET inhibition + gemcitabine)." (PMID 29100344, 2017). "A proteolytically inert mutant of pro-HGF confirmed the competitive antagonism between HGF and pro-HGF, and suppressed proliferation, motility and invasiveness of cancer cells in vitro and inhibited tumor growth and metastases in vivo." (PMID 28420162, 2017). "Finally, we tested the effects of WZB-117 and HGF in a stroma-tumor co-culture system using human colon myofibroblasts secreting approximately 1 μmol HGF/106 cells/24 hours and luciferase-expressing CRC cells." (PMID 28445144, 2017). "This indicates that novel mechanisms, such as WNK1 activation, may contribute to prosurvival activity of HGF in MET-amplified NSCLC cells and maintain the tumor-promoting crosstalk between tumor cells and cancer- associated fibroblasts." (PMID 28968967, 2017). "Interestingly, EGF stimulates anterograde lysosome trafficking through a different mechanism than previously reported for HGF, suggesting that there are redundant signaling pathways that control lysosome positioning and trafficking in tumor cells." (PMID 28978320, 2017).
tumor (continued). "Although we do not fully understand this discrepancy yet, it is possible that HGF stimulation causes a diffuse infiltration of single cells into the cerebellum tissue with no apparent proliferation of the primary tumour mass." (PMID 28706234, 2017). "The functional heterogeneity of PSCs in terms of HGF-mediated tumor-stroma interactions suggests that inhibition of the HGF pathway as a novel treatment approach in PDAC might have different effects in different subsets of patients." (PMID 29069737, 2017). "Combined inhibition of glucose metabolism and HGF/MET signaling (‘anti-METabolic therapy’) may represent a more effective CRC treatment compared to utterly blocking tumor blood supply." (PMID 28445144, 2017). "Thus, there is a possibility wherein single MB tumour cells in untreated/HGF co-culture did disseminate effectively as well but their microscopy detection failed due to low fluorescence." (PMID 28706234, 2017). "The mechanisms underlying the poor prognosis are not well understood although AFP has been reported to have a suppressive effect on lymphocyte transformation, to enhance tumor cell proliferation through the HGF and c-Met pathway, and to increase angiogenesis via VEGF expression." (PMID 28423604, 2017). "When HGF pathway was blocked by c-Met inhibitor, the tumour size was reversed." (PMID 28258248, 2017). "Local/tumor HGF expression conveyed a significant rescue of C-1 driven tumor growth inhibition (P < 0.001), suggesting local HGF expression may be required to mediate BRAF inhibitor resistance." (PMID 28147313, 2017). "Some of the differentially regulated genes were uniquely expressed in tumors and coded for extracellular proteins, i.e. HGF activator, thimet oligopeptidase, and kininogen, which defines them as potential tumor marker candidates and play a critical role in tissue repair and intracellular signaling." (PMID 29254206, 2017). "The present demonstration of a functional heterogeneity of PSCs in terms of HGF-mediated tumor-stroma interactions suggests that inhibition of the HGF pathway as a novel treatment approach in PDAC might have different effects in different subsets of patients." (PMID 29069737, 2017). "Abundant HGF makes the liver one of the common metastatic sites for multiple tumours." (PMID 28393839, 2017). "Once in close proximity to transformed cells in tumoral ducts, CAF favor tumor growth as a result of overexpression of hepatocyte growth factor (HGF), heparin-binding epidermal growth factor (HB-EGF), TGFβ and stromal cell-derived factor (SDF)-1 (also known as CXCL12)." (PMID 28098760, 2017). "Moreover, elevated HGF serum levels, after surgery, is able to predict early tumor recurrence and metastasis." (PMID 28077782, 2017). "In particular, the combination treatment of TAK-701 and gefitinib markedly reduces tumor growth in HCC827-HGF cell xenografts, a human NSCLC cell line with an activating EGFR mutation and HGF overexpression; this treatment also inhibited phosphorylation of c-MET, EGFR, ERK, and Akt." (PMID 28817103, 2017). "Because miR-7 acts as a tumor suppressor, the HGF/miR-7 pathway could potentially explain the tumor-suppressive effects of HGF in normal cells." (PMID 29133945, 2017). "Conversely, FGF, EGF, and HGF can influence tumor cells in both autocrine and paracrine fashions." (PMID 27965469, 2017). "Therefore, the smaller 64Cu-NOTA-rh-HGF displayed a faster circulation clearance than radiolabeled intact mAbs, which also obtained a higher optimal tumor/muscle ratio (13.5 ± 6.1 at 9 h p.i. in U87-MG xenografts) in less than a half-life period." (PMID 28485003, 2017). "First, inhibition of HGF-mediated cMET phosphorylation was tested in tumor cells in vitro." (PMID 29228696, 2017). "A complicating factor with the model was a significantly higher tumor load in the Dct-survivin × HGF/SF hybrid (two-fold), which could have contributed to the metastasis phenotype." (PMID 28788083, 2017).
tumor (continued). "On one hand, tumor hypoxia -exacerbated by anti-angiogenic drugs- sensitizes surviving CRC cells to paracrine HGF stimulation, which enhances tumor cell motility and invasion, thus allowing CRC cells to escape therapy and to form secondary colonies in distant organs." (PMID 28445144, 2017). "We therefore reasoned that selective targeting of GLUT1 would have been a cleaner and more effective therapeutic approach compared to generalized cutting of tumor blood supply, and that neutralization of HGF would have overcome micro-environment-mediated resistance to glucose uptake blockade." (PMID 28445144, 2017). "HGF further supports HNSCC tumor development through the promotion of angiogenesis." (PMID 28441771, 2017). "Also, recent clinical trials have revealed the efficacy of onartuzumab and ficlatuzumab, antibodies against c-Met and HGF, respectively, in preventing tumor progression of solid tumors, including HCC." (PMID 28587113, 2017). "However, the tumour volume reduction in the HGF-treated tumours was obviously less than the control and c-Met inhibitor-treated tumours." (PMID 28258248, 2017). "Monitoring changes in total MET and tumor HGF levels may have clinical utility for identifying patients most likely to benefit from combination therapy with inhibitors targeting the MAPK pathway and HGF/MET signaling." (PMID 28147313, 2017). "In contrast, the tumor suppressive functions of HGF in cancer is sparsely known." (PMID 29133945, 2017). "We could not detect a significant increase in the in vitro invasive properties of the different tumor cell lines or the primary BRCAs in co-culture, despite the significantly higher HGF concentration." (PMID 28545495, 2017). "In addition, resistance to an anti-EGFR antibody was also induced in tumor cells by the co-culture of cancer cells and HGF-producing lung fibroblasts." (PMID 28619066, 2017). "Importantly, HGF/c-Met signaling is crucial in the context of communication between cancer cells and the the tumor stroma." (PMID 28212658, 2017). "HCC cell-derived exosomes transfer of the soluble factor HGF may contribute to the regulation of the tumor microenvironment." (PMID 27716356, 2016). "Most of these studies reported an upregulation of proangiogenic factors like VEGF, PDGF, PlGF and HGF during therapy, which may reflect an increase of tumor hypoxia during antiangiogenic therapy." (PMID 26956051, 2016). "In LAC cells with acquired resistance to Epidermal Growth Factor Receptor Tyrosin Kinase Inhibitor (EGFR-TKI), we found that a part of tumor cells were much more sensitive to HH or HGF/MET inhibitors, suggesting an oncogenic addiction shift from EGFR to HH and HGF/MET pathways." (PMID 27015549, 2016). "Thus, inhibitors of HGF activation, such as SRI 31215, represent a novel approach to block the crosstalk between tumor cells and fibroblasts, neutralizing the tumor-promoting activity of cancer-associated fibroblasts." (PMID 27121052, 2016). "Migration of tumor cells to target organs is driven by cytokines, including HGF." (PMID 26934743, 2016). "Increases in HGF in the tumor microenvironment contribute to this angiogenic switch, while cMET signaling by the cancer cells facilitates invasion and migration away from the hypoxic interior of the tumor, entry into the new and leaky vessels, and metastasis to distant locations." (PMID 27057482, 2016). "In a murine model of colitis-associated carcinoma, tissue-restricted deletion of fibroblast Iκκβ led to upregulation of the TGFβ genetic signature and promotion of colonic tumor growth, suggesting a tumor-suppressive function of CAF Iκκβ dependent on the release of hepatocyte growth factor." (PMID 26828520, 2016). "However, an aberrant MET/HGF axis results in cell migration and survival and promotes tumor development and progression." (PMID 27013592, 2016). "In addition, TANs promoted tumor invasion by releasing of ROS, growth factors such as hepatocyte growth factor (HGF), and cytokines like oncostatin M." (PMID 27446967, 2016).
tumor (continued). "MET is an oncogene that, when activated by its ligand HGF, exhibits potent migration/invasion-inducing activity and is frequently expressed in OS and is strictly related to its aggressiveness, and found relevant for the pathogenesis of this tumor." (PMID 27851822, 2016). "Moreover, HCC cell-derived exosomes exerted their functions by increasing the level of proteins related to sorafenib resistance, protecting tumor cells from sorafenib-induced apoptosis and activating the HGF/c-Met/Akt pathway in vitro." (PMID 27716356, 2016). "As a result, HGF injection resulted in an increase of tumor size and weights." (PMID 27525306, 2016). "They suggested that post-translational modifications of growth factors, such as HGF, might be one of the mechanisms that promotes tumor growth via factors produced by the microenvironments." (PMID 27917934, 2016). "Furthermore, HGF levels were correlated with tumor size, node cirrhosis, tumor recurrence or metastases in HCC patients." (PMID 27013592, 2016). "In addition, HVS caused a dose-dependent inhibition of HGF-induced, but not epidermal growth factor (EGF)-induced, cell scattering in addition to HGF-mediated migration, invasion, and 3-dimensional (3D) proliferation of tumor cell spheroids." (PMID 27086914, 2016). "Recent studies demonstrate that not only osteoclasts (OCs), but also osteoblasts (OBs) play a central role in the pathogenesis of skeletal metastases, partly by producing hepatocyte growth factor (HGF), which promotes tumor cell migration and seeding into the bone." (PMID 26934743, 2016). "Aberrant HGF/MET axis activation has been implicated in the progression of multiple human tumor types, including liver, lung and gastric carcinomas, and results in cell survival and migration and tumor development and progression." (PMID 27013592, 2016). "In tissues, high expression of miR-26a-5p could suppress tumor angiogenesis in HCC by targeting HGF-cMet signaling, and it was a novel prognostic biomarker for HCC84." (PMID 27917899, 2016). "Met, pMet, and HGF was expressed in 33%, 53%, and 49% of the tumours, respectively." (PMID 27175600, 2016). "HGF/MET signaling pathway activation can occur via MET gene amplification, overexpression, mutations or paracrine and autocrine activation of MET by HGF, all of which have been observed in multiple human tumor types." (PMID 27013592, 2016). "The hepatocyte growth factor and its receptor have been described to be associated not only with high tumor grade and poor prognosis of a number of cancers, but also with migration and development of distant metastasis." (PMID 27851822, 2016). "Furthermore, there are multiple reports of TKI resistance, often through kinase crosstalk as well as overabundance of growth factors, like HGF (Entrez Gene: 3082), in the surrounding tumor microenvironment." (PMID 27127175, 2016). "In addition to inhibiting tumors with MET gene amplification, ABT-700 also inhibits the subcutaneous xenograft growth of human tumor cell lines that have c-Met protein overexpression or autocrine HGF." (PMID 26879245, 2016). "Finally, in the experimental mouse model, we showed that curcumin inhibited HGF-stimulated tumor growth and induced an increase in E-cadherin expression and a decrease in vimentin, CD34, and vascular endothelial growth factor (VEGF) expression." (PMID 27525306, 2016). "Particularly, HGF signaling through its cognate receptor, c-Met, can induce cancer cells to undergo an EMT typified by loss of cell-cell adhesions and increased cell motility, leading to tumor cell invasion and metastasis; the same is true for EGF signaling." (PMID 27127175, 2016). "In fact, provocative results published by Straussman and colleagues showed that therapy resistance exhibited by tumor cell lines that harbor the BRAF (V600E) mutation was mediated by receptor activation (MET) and stromal-cell derived Hepatocyte Growth Factor (HGF)." (PMID 26227631, 2015).